SHBG (sex hormone binding globulin)
Diseases named in the same sentence as SHBG in open-access papers (continued):
Sharing a sentence is not in itself a finding about the gene and the disease.
Hyperinsulinemia (continued). "An increase in cell androgen production and hyperinsulinemia reduces sex hormone binding globulin (SHBG) to increase circulating testosterone levels." (PMID 36648830, 2023). "Hyperinsulinemia also affects the inhibition of hepatic SHBG synthesis, thereby increasing free testosterone concentrations." (PMID 36986218, 2023). "Hyperinsulinemia suppresses the production of sex hormone-binding globulin resulting in elevated level of free testosterone." (PMID 36941638, 2023). "Due to hyperglycemia and hyperinsulinemia, the hepatic sex hormone binding globulin (SHBG) decreases, which exacerbates the effect of luteinizing hormone and excessive androgen production." (PMID 36837921, 2023). "It starts a self-propagating positive feedback loop by lowering SHBG concentration and aggravating IR, exacerbating the HA or hyperinsulinemia symptoms over time." (PMID 37108615, 2023). "Studies have proven that reduced SHBG levels, HA, hyperinsulinemia, and T2D are the primary symptoms of PCOS." (PMID 37108615, 2023). "Hyperinsulinemia increases androgen production (by stimulating ovarian steroidogenesis) and inhibits sex hormone-binding globulin (SHBG) production." (PMID 36523331, 2022). "Decreased synthesis of sex hormone-binding globulin (SHBG) related to hyperinsulinemia is one of the disturbances characteristic of polycystic ovary syndrome (PCOS)." (PMID 35140785, 2022). "In obese adolescents, it is related to hyperinsulinemia, which can stimulate ovarian and adrenal androgen production, as well as decrease the synthesis of sex hormone binding globulin (SHBG) in the liver, leading to excess androgen." (PMID 36145182, 2022). "Hyperinsulinemia contributes to fetal hyperandrogenism exposure by stimulating androgen production, inhibiting placental aromatase activity and inhibiting SHBG." (PMID 36733795, 2022). "Hyperinsulinemia decreases hepatic production of sex hormone-binding globulin (SHBG) resulting in increased androgen bioavailability (i.e., increased free testosterone), and these abnormalities appear to reverse with weight loss." (PMID 35412268, 2022). "Hyperinsulinemia in these disorders and subsequent direct stimulation of androgen production, inhibition of SHBG and inhibition of placental aromatase activity, contributes to hyperandrogenism." (PMID 36733795, 2022). "IR in these patients can create hyperinsulinemia which increases serum free androgen levels through increasing the hepatic generation of sex hormone binding globulin (SHBG), and androgen production by ovarian theca cells." (PMID 35883082, 2022). "For a long time, it was thought that the common denominator of reduced SHBG synthesis was hyperinsulinemia." (PMID 36235799, 2022). "IR and the associated hyperinsulinemia promotes a pituitary LH release, a rise in testosterone production and an inhibiting SHBG (sex hormone binding globulin) synthesis, leading to high levels of free testosterone (FT)." (PMID 36678524, 2022). "In general, an increased BMI in children of this age is related to earlier adrenal and gonadal maturation, while adiposity in girls is related to higher levels of testosterone and lower levels of SHBG, in part due to hyperinsulinemia." (PMID 34499672, 2021). "As early as the 1990s, hyperinsulinemia was found to be an important factor for the suppression of SHBG production in PCOS." (PMID 33429918, 2021). "In PCOS, the resulting hyperinsulinemia inhibits hepatic synthesis of sex hormone binding globulin (SHBG), leading to increased circulating free androgens." (PMID 34684492, 2021). "The resulting hyperinsulinemia inhibits hepatic synthesis of SHBG, leading to an increased circulating free androgens." (PMID 34684492, 2021). "Since SHBG normally binds T with a greater affinity than E2, the downstream effect of hyperinsulinemia tends to be hyperandrogenic." (PMID 34572562, 2021). "For example, excess adiposity leads to hyperinsulinemia which acts, in turn, to suppress circulating SHBG levels." (PMID 33723399, 2021).
Hyperinsulinemia (continued). "Hyperinsulinemia can increase androgen and free androgen production by reducing androgen binding with SHBG." (PMID 33514384, 2021). "MF administration increases the production of SHBG, by reducing body weight and hyperinsulinemia, and, thereby, reduces the signs of HA in PCOS women." (PMID 33429918, 2021). "Obesity and hyperinsulinemia, if present, further lead to increased aromatization of androgens and decreased production of SHBG, the results of which are increased levels of bioavailable estrogen." (PMID 32911852, 2020). "Hyperinsulinemia and InsR induce ovarian androgen synthesis and reduce serum sex hormone-binding globulin (SHBG) concentrations, which leads to increased levels of free testosterone." (PMID 32252239, 2020). "In premenopausal women, hyperinsulinemia promotes the stimulation of ovarian androgen synthesis and decreases hepatic production of SHBG." (PMID 32911852, 2020). "This condition can be exacerbated by hyperinsulinemia, leading to further reduction and stimulation of ovarian androgen production by SHBG, excessive secretion of luteinizing hormone, and increased ratios of androgen to estrogen." (PMID 33343510, 2020). "Hyperinsulinemia can reduce the production of SHBG in the liver and decrease the circulating SHBG levels, thus increasing the level of bioavailable free androgens." (PMID 32733580, 2020). "A crucial role for IR, and compensatory hyperinsulinemia, in the suppression of SHBG levels has been strongly supported by a clear inverse relationship between serum insulin and SHBG levels." (PMID 31402895, 2019). "In humans, lower GH and SHBG levels are also associated with polycystic ovarian syndrome (PCOS), characterized by menstrual abnormalities, hyperinsulinemia, and hyperandrogenism." (PMID 31071082, 2019). "Hyperinsulinism results in hyperandrogenism by increasing LH induced androgen synthesis and decreasing sex hormone binding globulin." (PMID 31423417, 2019). "Hyperinsulinemia also alters the gonadotropin-releasing hormone (GnRH) pulse secretion pattern, suppresses the sex hormone-binding globulin (SHBG) and potentiates ovarian androgen production in women with PCOS." (PMID 27092084, 2016). "High carbohydrate (CHO) diet leads to hyperinsulinemia and reduced sex hormone binding globulin (SHBG)." (PMID 27157182, 2016). "Insulin resistance leads to hyperinsulinemia, reduces SHBG and raises free circulating testosterone and together, hyperandrogenism and hyperinsulinemia impairs ovarian follicle development." (PMID 25866568, 2015). "Hyperinsulinemia increases androgen levels by reducing the levels of sex hormone-binding globulin, which can negatively affect the ovulation." (PMID 25083180, 2014). "Both short and long term high-lipid, low-fiber diets have been associated with hyperandrogenemia, possibly acting through intake-induced hyperinsulinemia, which would lower SHBG synthesis, increasing androgen availability." (PMID 25763405, 2014). "Women with PCOS often display low levels of SHBG, and in addition to this, hyperinsulinemia can also decrease the level of SHBG, thus increasing the levels of bioactive testosterone." (PMID 25158044, 2014). "The hyperinsulinemia of PCOS appears to increase androgen secretion from the ovary as well as to decrease circulating sex hormone binding globulin (SHBG)." (PMID 16359551, 2005). "For women, IR and hyperinsulinemia lower Sex Hormone-Binding Globulin levels, increasing free sex hormones, while IGF-1 interacts with insulin signaling and hormone receptors, collectively promoting the development of hormone-sensitive tumors in women, such as breast and endometrial cancer." (PMID 41419984, 2025). "Additionally, hyperinsulinemia suppresses hepatic production of SHBG, further increasing levels of circulating free testosterone and amplifying the metabolic risks associated with androgen excess." (PMID 40443457, 2025).
Hyperinsulinemia (continued). "Moreover, the combination of hyperinsulinemia and low vitamin D further disrupts hormonal balance by promoting ovarian androgen production and decreasing SHBG levels, thereby increasing the bioavailability of testosterone." (PMID 40868057, 2025). "Prolonged hyperinsulinemia reduces bioavailable sex hormone-binding globulin (SHBG) and increases circulating estrogens and androgens, which may further promote carcinogenesis." (PMID 39860425, 2025). "Additionally, hyperinsulinemia reduces sex hormone-binding globulin (SHBG) concentrations, leading to increased bioavailability of estrogen, which is implicated in hormone-sensitive cancers." (PMID 41367907, 2025). "At the same time, hyperinsulinemia decreases SHBG levels, increasing free estrogen levels." (PMID 41375041, 2025). "Hyperinsulinemia increases serum free testosterone levels by reducing the production of hepatic sex hormone-binding globulin (SHBG), stimulates androgen production triggered by LH and insulin-like growth factor 1 (IGF-1), and enhances IGF-1 bioactivity by suppressing IGF-binding protein production." (PMID 40362363, 2025). "Additionally, hyperinsulinemia lowers SHBG levels, increasing the availability of sex hormones like estrogen, thereby heightening the risk of hormone-dependent cancers." (PMID 39290325, 2024). "Further, the synthesis and regulation of sex hormone-binding globulin (SHBG) may be influenced by hyperinsulinemia." (PMID 39741509, 2024). "In addition, free E2 is increased in the circulation in the context of hyperinsulinemia, due in part to insulin down-regulation of sex-hormone-binding globulin (SHBG)." (PMID 38652231, 2024). "However, hyperinsulinemia has the potential to inhibit hepatic SHBG secretions, thereby leading to a decline in SHBG levels in circulation." (PMID 39741509, 2024). "Women with PCOS frequently exhibit hyperinsulinemia; this may induce sex hormone-binding globulin (SHBG) inhibition." (PMID 39064680, 2024). "Besides androgen, insulin and insulin-like growth factor-1 can contribute to hair follicle growth and also hyperinsulinemia, which suppress the sex hormone-binding globulin, a modulator of testosterone bioavailability." (PMID 39336541, 2024). "In individuals with hyperinsulinemia, elevated insulin levels reduce SHBG." (PMID 39290325, 2024). "The National Institute for Health and Care Excellence states that since there is a substantial inverse relationship between SHBG levels and fasting serum insulin in obese women, measuring SHBG levels can serve as a proxy measure for the severity of hyperinsulinemia in PCOS-affected women." (PMID 38389707, 2024). "Additionally, hyperinsulinemia inhibits the liver’s production of SHBG, leading to increased testosterone levels in the blood." (PMID 38892561, 2024). "As hyperinsulinemia suppresses the production of SHBG, this could lead to a vicious circle leading to pronounced hyperinsulinemia via a compensatory increase in β-cell production of insulin." (PMID 39055720, 2024). "Moreover, chronic hyperinsulinemia can promote tumorigenesis in estrogen-sensitive tissues since it reduces the concentration of sex hormone-binding globulin (SHBG) in the blood and increases the bioavailability of estrogens." (PMID 38396914, 2024). "Biochemical characteristics of increased adiposity were studied in SGA girls, showing they were more likely to develop hyperinsulinism, hypoadiponectinemia, hyperleptinemia, dyslipidemia, lower sex hormone binding globulin, higher dehydroepiandrosterone sulfate, and advanced bone maturation." (PMID 39240976, 2024). "In addition, a significant negative correlation between HOMA-IR and SHBG was found (r = −0.408; p < 0.001), which is in line with previous findings in patients with PCOS and likely due to hyperinsulinism inhibiting SHBG synthesis and secretion." (PMID 39768704, 2024). "Chronic hyperinsulinemia lowers the levels of sex hormone-binding globulin (SHBG)." (PMID 37509506, 2023).
Hyperinsulinemia (continued). "In turn, compensatory hyperinsulinemia inhibits SHBG synthesis in the liver." (PMID 36968815, 2023). "Compensatory hyperinsulinemia inhibits hepatic SHBG synthesis." (PMID 36968815, 2023). "By peripherally inhibiting hepatic synthesis, hyperinsulinemia decreases serum sex hormone binding globulin (SHBG), favoring free circulating androgens, and decreasing insulin-like growth factor binding protein-1 (IGFBP-1), allowing more IGF-1 to be accessible locally and peripherally." (PMID 37791160, 2023). "Moreover, hyperinsulinemia decreases the hepatic excretion of sex hormone-binding globulin (SHBG), which consequently leads to increased androgen bioavailability (i.e., increased free testosterone)." (PMID 38136107, 2023). "Hyperinsulinemia aggravates the hormonal and ovulatory dysfunctions by inducing an excessive production of androgens and a decrease in serum sex hormone binding globulin (SHBG)." (PMID 34983571, 2022). "A mere 5% reduction in body weight could reduce IR, hyperinsulinemia, and HA; increase SHBG production, and improve abnormal reproductive measures." (PMID 36147577, 2022). "Hyperinsulinemia and hyperandrogenemia can hinder the secretion and synthesis of SHBG in the liver." (PMID 35615684, 2022). "We therefore hypothesize that like outside pregnancy, hyperinsulinemia in these disorders and subsequent direct stimulation of androgen production, and inhibition of SHBG (that binds androgens), contributes to hyperandrogenism." (PMID 36733795, 2022). "There was a strong relationship between insulin and SHBG, and SHBG could be a marker for either hyperinsulinemia, IR, or both, in obese children (aged 6–9 years)." (PMID 35684072, 2022). "In addition, hyperinsulinemia inhibits the synthesis of SHBG [Sex hormone-binding Globulin] leading to increased free sex hormone levels thus promoting sex hormone-dependent cancers such as endometrial, breast and prostate cancers." (PMID 33920079, 2021). "The reason why this may occur has been investigated during the last three decades; initially, it was suggested that hyperinsulinemia was the main factor reducing plasma SHBG levels." (PMID 33689083, 2021). "Compensatory hyperinsulinemia and IR inhibit the hepatic synthesis and secretion of SHBG." (PMID 33514384, 2021). "Moreover, hyperinsulinemia increases bio-available serum testosterone by inhibiting the hepatic synthesis of sex hormone-binding globulin (SHBG)." (PMID 33322590, 2020). "Moreover, hyperinsulinemia reduces the circulating level of sex hormone-binding globulin (SHBG) and increases free testosterone (FT), which inhibits follicular maturation with consequent menstrual irregularity and infertility." (PMID 32490533, 2020). "Meanwhile, the levels of testosterone and SHBG are increased in women with MetS, which may blunt the effect of hyperinsulinemia." (PMID 32973687, 2020). "In addition, hyperinsulinemia can decrease sex-hormone-binding globulin that can increase estrogen concentration and enhance estrogen receptor activation through IGF-I signaling." (PMID 32369516, 2020). "In addition, this hyperinsulinemia decreases the hepatic generation of sex hormone binding globulin (SHBG)." (PMID 33133563, 2020). "Furthermore, an increase in abdominal adipose tissue, stimulated by compensatory hyperinsulinemia, creates an imbalance in sex steroids with decreased sex hormone binding globulin (SHBG) levels and increased free androgens levels." (PMID 30934676, 2019). "Hyperinsulinemia could increase androgen and free androgen production by reducing the binding of androgen with sex-hormone binding globulin (SHBG)." (PMID 29426356, 2018). "Hyperinsulinemia stimulates ovarian androgen production and decreases sex-hormone-binding globulin." (PMID 30065244, 2018). "Alternatively, hyperinsulinemia may reduce the level of SHBG, leading to a high FAI value, and thereby amplification of the effect of androgens." (PMID 27886515, 2017).
Hyperinsulinemia (continued). "Specifically, hyperinsulinemia may negatively impact the binding of sex hormones with sex hormone binding globulin (SHBG) and consequently be related to increases in free sex hormone levels, which play a role in higher bone mass." (PMID 28704413, 2017). "Hyperinsulinemia leads to alteration of the secretion of gonadotropin-releasing hormone (GnRH) and to inhibition of the hepatic synthesis of sex hormone-binding globulin (SHBG), leading to increased concentration of circulating free androgens." (PMID 28642705, 2017). "We interpreted that the variation in SHBG levels might mostly result from the effects of IR/hyperinsulinemia upon hepatic SHBG production." (PMID 25223276, 2014). "The negative correlation between BMI and SHBG might be the result of hyperinsulinism, because insulin has shown to be an important inhibitor of hepatic SHBG output." (PMID 25408743, 2014). "Furthermore, hyperinsulinemia decreases SHBG levels increasing the amount of free testosterone available to act on target organs." (PMID 16095537, 2005). "We speculate that reduction in hyperinsulinemia due to the LCKD would decrease stimulation of ovarian androgen production as well as increase SHBG levels, synergistically limiting the amounts of circulating free-androgens in the serum." (PMID 16359551, 2005). "In addition, hyperinsulinemia decreases the production of sex hormone-binding globulin (SHBG) from the liver and increases the sensitivity of adrenal steroidogenesis to adrenocorticotropic hormone (ACTH) stimulation, both of them contributing to hyperandrogenism." (PMID 40066975, 2025). "Importantly, insulin resistance and hyperinsulinemia may drive pubertal gynecomastia by increasing aromatase activity, altering SHBG levels, and elevating the E2/T ratio." (PMID 39797240, 2024). "Additionally, it has been suggested that menstrual cycle disorders in obese women may be related to disorders of estrogen metabolism, changes in the concentration of SHBG, hyperinsulinemia, and changes in leptin levels." (PMID 38769497, 2024). "Additionally, hyperinsulinemia reduces SHBG levels, thereby increasing the free androgens." (PMID 38892561, 2024). "Reduced SHBG and IGF, preferentially insulin-like growth factor-binding protein 1 (IGFBP-1, also known as placental protein 12 or PP12), have been reported to be associated with hyperinsulinemia and represented as critical biomarkers/indicators of the metabolic syndrome." (PMID 37108615, 2023). "The explanation for this vicious circle lies in the fact that compensatory hyperinsulinemia could increase the sensitivity of granulosa cells to luteinizing hormone (LH) and further increase androgen release by theca cells while decreasing sex hormone-binding globulin production by the liver." (PMID 35739998, 2022). "Hyperinsulinemia caused by IR is believed to promote HA in PCOS because insulin may augment luteinizing hormone (LH)-induced androgen production and reduce the liver’s sex hormone-binding globulin (SHBG) synthesis." (PMID 36147577, 2022). "Notably, hyperinsulinemia is one of the factors inhibiting SHBG synthesis in the liver." (PMID 35140785, 2022). "To assess whether differences in TT and FT concentrations between clinical subgroups are related to degree of hyperinsulinemia and SHBG levels, we compared fasting insulin and SHBG, where available, in patients aged >10 years with lipodystrophy, insulin signaling defects or idiopathic SIR." (PMID 33901270, 2021). "Furthermore, PCOS women with hyperinsulinemia had low levels of SHBG." (PMID 33033446, 2020). "In addition, IR, hyperinsulinemia and LH could enhance androgen secretion by the ovaries and reduce the synthesis of sex hormone binding globulin (SHBG) in the liver." (PMID 33362718, 2020).